CD27 (CD27 molecule)
Diseases named in the same sentence as CD27 in open-access papers (continued):
Sharing a sentence is not in itself a finding about the gene and the disease.
malaria (27 papers, 2011 to 2024). Malaria is a serious and sometimes fatal disease caused by a parasite that commonly infects a certain type of mosquito which feeds on humans. "At baseline, in a malaria-naive individual, 76%–78% of Vδ1+ T cells expressed a CD27+ Tnaive phenotype." (PMID 35613583, 2022). "Here, the impact of a malaria episode on the expression of FcRL5 on the cell surface of naïve B cells (CD21+CD27−), classical MBCs (CD21+CD27+), activated MBCs (CD21−CD27+), and atypical MBCs (CD21−CD27−) was evaluated by flow cytometry." (PMID 34758841, 2021). "A decline in the frequency of IgD+CD27+ memory B cells was observed in circulation of infants from malaria-endemic regions relative to those from an area with unstable malaria transmission at all ages." (PMID 22166136, 2011). "More recently, CD21– CD27– atBCs in 14 malaria-exposed children were described as switched B cells." (PMID 35722474, 2022). "In chronic infection settings such as HIV-1, malaria or tuberculosis, the memory B cell population characterized by low expression of CD27 and CD21, sometimes referred to as “atypical”, “tissue-like” or “exhausted”, can comprise up to 40-50% of the memory B cell pool in PBMCs." (PMID 36582240, 2022). "As CD27- B cells encompass both naïve and atypical memory B cells, the latter appearing in several chronic infectious diseases including malaria, tuberculosis and HIV, we addressed the presence of atypical memory B cells but found similar frequencies of these cells in small and large tonsils." (PMID 34745084, 2021). "Our recent studies provided evidence that relative to classical MBCs (CD19+ CD21+ CD27+), atypical MBCs (CD19+ CD21−CD27−) isolated from peripheral blood of adults with lifelong exposure to malaria differentially upregulated TBX21 that encodes T-bet, the Th1-lineage defining transcription factor." (PMID 31068937, 2019). "Despite this transformation, absence of CCR2 completely abolished the disappearance of BM myeloid progenitors, for both “CD27+ CMPs” (60.6±5.0×103 cells uninfected, 50.7±7.2×103 cells day 7 p.i.)and “GMPs” (41.8±8.4×103 cells uninfected, 59.3±6.5×103 cells day 7 p.i.), during acute malaria." (PMID 23762028, 2013). "Here, for malaria, we report that the frequency of total CD27– EMRA CD8+ T cells and the frequency of IFN-γ+CD27– EMRA CD8+ T cells was high at c–1 in the protected group in contrast to their EM counterpart." (PMID 38716733, 2024). "Chronic immune activation also affects circulating IgM+CD19+CD27+ MBC, which frequency is greatly reduced in HIV and malaria." (PMID 28878766, 2017). "We propose that in a context of chronic malaria exposure, MZ-like B cells undergo GC-independent affinity maturation, by first upregulating b220 expression and then downregulating IgD, CD21, and CD27 to generate early IgM short-lived MBC." (PMID 28878766, 2017). "A CD27−CD21− B‐cell population termed “atypical B cells” was found in blood samples from malaria patients and those with prior exposure to Plasmodium antigens and was confirmed to be double‐negative for IgD and CD27 by recent studies." (PMID 37272217, 2023). "Furthermore, for Vδ1+ and Vδ3+ T cells, similar phenotypes of naïve (CD27+) and type 1 effector (CD16+) cells were observed, while the proportion of CD16+ Vδ1+ T cells was highest in children with asymptomatic malaria." (PMID 35250979, 2022). "Considering the nature of malaria exposure and the consistent correlation between BAFF and both total and Pf+ proportions of IgG+ MBC and CD27− MBC, one can hypothesize that BAFF in relation to P. falciparum could have a specific impact on the B cell response." (PMID 33465125, 2021). "BAFF levels correlate with IgG+ MBC and CD27− MBC of both total and Pf+ compartments in infants, suggesting that BAFF could play a role in the development of naturally acquired immunity against malaria." (PMID 33465125, 2021).
malaria (continued). "Most of MBC sub-set studies reported total populations which phenotyped as CD19+CD21−CD27− (atypical MBCs) or CD19+CD27+ (classical MBCs), without any malaria specificity." (PMID 31783870, 2019). "The median ratios of memory to naive B cells (indicated by the presence or absence of CD27 expression) were not significantly different in children with malaria compared to controls." (PMID 26581890, 2015). "Infants from the malaria-endemic area had higher overall numbers of CD19+ B cells but reduced populations of circulating IgD+CD27+ memory B cells and expanded populations of CD10+CD34- immature transitional B cells at all ages relative to infants living in an area with unstable malaria transmission." (PMID 22166136, 2011). "In malaria endemic areas, people often have increased levels of atypical memory B-cells in the blood, and in this assay it was demonstrated that when parasites were present there was an increase in the proportion of CD19 + CD20 + CD27 − FCRL4 + B-cells, and a contraction of classical memory B-cells." (PMID 34225761, 2021). "Early exposure to P. falciparum may interfere with splenic development and/or disrupt splenic architecture in infants from malaria-endemic region, which could be one possible explanation for the diminution of CD19+IgD+CD27+ B cells observed in the cohort of infants from Kisumu." (PMID 22166136, 2011). "For example, atypical MBCs in malaria-experienced individuals contained secretory immunoglobulin transcripts, suggesting that these are antibody-secreting cells, while classical CD21+CD27+ MBCs in the same individuals did not." (PMID 34758841, 2021). "Since exposure to holoendemic malaria has been shown to suppress non-class switched (CD19+IgD+CD27+) MBC populations, we evaluated the effect of reduced malaria transmission on the marginal zone B cells (CD19+IgD+CD27+IgM+), a subset of this B cell population." (PMID 23826242, 2013).
tuberculosis (21 papers, 2011 to 2025). A chronic, recurrent infection caused by the bacterium Mycobacterium tuberculosis. "Loss of CD27 expression on M. tuberculosis–specific IFN-γ+ CD4+ T cells has been shown to be associated with tuberculosis when compared to LTBI in multiple studies." (PMID 28329119, 2017). "On the other hand, detailed research on B cells from patients with tuberculosis showed enrichment of CD27 + CD38- memory B cells in lung tissue compared to blood, which was dominated by CD27-CD38- naive and CD27-CD38+ transitional B cells." (PMID 39449326, 2024). "It was found that NK cells expressing CD27+ in the lung aggregated during the latent period of tuberculosis." (PMID 37901241, 2023). "CD27 staining was included in the flow cytometry assays for 17 cases of tuberculosis, 8 cases of recently acquired LTBI, and 8 cases of remotely acquired LTBI." (PMID 28329119, 2017). "Others have also demonstrated that measuring the levels of CD27 expression on M. tuberculosis–specific cytokine-producing CD4+ T cells has the potential to distinguish between tuberculosis and LTBI." (PMID 28329119, 2017). "M. tuberculosis–specific immune signatures that incorporate CD27 have shown promise in distinguishing between tuberculosis and LTBI." (PMID 28329119, 2017). "Recently, a T-cell-activation marker-tuberculosis (TAM-TB) assay that measures the CD27 phenotype of IFN-γ producing cells was shown to have good performance characteristics in children." (PMID 32131556, 2020). "M. tuberculosis antigen-specific CD27− CD4+ memory T lymphocytes have been proposed as a quick blood-based tool to diagnose active TB." (PMID 22778764, 2012). "T cells from tuberculosis patients showed aberrantly high expression of activation markers (i.e., CD38 and HLA-DR) and reduced levels of the TCR coreceptor CD27." (PMID 34035497, 2021). "Previous studies have verified some cytokine secretion profiles from CD4+ T cells in patients with tuberculosis, such as IFN-γ+, TNF-α, IL-2 and CD27." (PMID 34176483, 2021). "M. tuberculosis–specific IFN-γ+ responses were analyzed for 2 such signatures—the change in intensity of CD27 expression (determined by the TAM-TB assay) and the proportion of both CD45RA−CD27− and CD45RA−CD27+ phenotypes—and these signatures were compared between groups." (PMID 28329119, 2017). "For example, the TAM-TB assay, which evaluates the ratio of the median fluorescence intensity of CD27 within the whole CD4+ T-cell population to that of CD27 in the M. tuberculosis–specific IFN-γ+ CD4+ T cells has been shown to distinguish between tuberculosis in LTBI in children and adults." (PMID 28329119, 2017). "The results indicated that the frequencies of cytokine-secreting Mtb-specific CD4 T cells with the CD38+CD27– phenotype clearly distinguished individuals with active tuberculosis from those without the disease." (PMID 40406513, 2025). "The study by Ahmed showed Phenotypic changes of MTB-specific T cells are potential surrogate markers for tuberculosis treatment efficacy and can help to discriminate between aTB [profile: CD38(pos), CD27(low)) and latent MTB infection (CD38(neg), CD27(high)], which is consistent with our results." (PMID 36457066, 2022). "We studied here the expression of Mip-1β and the T cell maturation marker CD27 within CMVpp65-specific CD4+ and CD8+ T cells in relation to age, HIV and active Tuberculosis (TB) co-infection in a cohort of Tanzanian volunteers (≤16 years of age, n = 108 and ≥18 years, n = 79)." (PMID 25974183, 2015). "Interestingly, we found that CD27 and PD-1 also distinguish LTBI individuals from those who have clinically resolved Mtb infection after anti-tuberculosis treatment." (PMID 22545156, 2012). "Using statistical models, we determined that CD27 and PD-1 predicted LTBI versus BCG status in healthy individuals and distinguished LTBI individuals from those who had clinically resolved Mtb infection after anti-tuberculosis treatment." (PMID 22545156, 2012).
tuberculosis (continued). "This assay is able to discriminate between active TB and LTBI by analyzing CD27 expression on specific M. tuberculosis CD4+ T-cells that respond secreting IFN-γ." (PMID 30687314, 2018). "The percentage of CD27− and/or CCR4+ surface homing markers was studied on active TB and LTBI within the IFN-γ+CD4+ T-cells subset after M. tuberculosis specific stimulation." (PMID 30687314, 2018). "In summary, our findings on surface homing markers such as CD27 and CCR4 on M. tuberculosis specific CD4+ T-cells gather the required features for using them as potential TB biomarkers." (PMID 30687314, 2018). "Furthermore, a recent study showed that the reduced expression of CD27 on M. tuberculosisantigen-specific CD4+ cells correlated better with persistent active tuberculosis rather than newly diagnosed active tuberculosis." (PMID 22778764, 2012). "The objective was to study the capacity of a new biomarker, the expression of the T cell maturation marker CD27 on MTB-specific CD4 T cells, to identify active tuberculosis (TB) disease in subjects from a MTB and HIV endemic region." (PMID 22087280, 2011). "In addition, the TAM-TB assay, which evaluates the ratio of the median fluorescence intensity of CD27 in the whole CD4+ T-cell population to that of CD27 in the MTB-specific IFN-γ+ CD4+ T cells, has a vital role in distinguishing between tuberculosis in LTBI in adults and children." (PMID 34176483, 2021).
lung carcinoma (20 papers, 2012 to 2026). "Strikingly, State_4 markers correlated with poor lung cancer prognosis, while State_3 markers associated with better outcomes, implying CD27+ B cells differentiate into malignant State_4 subsets." (PMID 41377765, 2025). "Elevated IREB2 expression correlated with accelerated lung‐function decline in COPD but predicted improved prognosis in lung cancer B cells, whereas higher CD27+ B cell levels in COPD were associated with protumorigenic activity." (PMID 41377765, 2025). "Moreover, we observed an association between CD27 on CD24+ CD27+ B cells and increased lung cancer risk." (PMID 38408977, 2024). "CD27 on CD24+ CD27+ B cell was identified to increase the risk of lung cancer in our research." (PMID 38408977, 2024). "Pleural effusion CD8+ T-cells from lung cancer patients express cell markers associated with a memory-like phenotype (CD45RA−CD45RO+CD27+Granzyme AlowPerforin−), similar to those markers found in CD8+ T-cells from chronic viral infections, which suggests that CD8+ T-cells may be exhausted." (PMID 23118782, 2012). "Using a genetically engineered mouse model of lung cancer, we show that tumors drive expansion of both CD27+ and CD27- γδ T cells." (PMID 41779856, 2026). "Previously it was shown patients with advanced lung cancer has high serum level of CD27 which correlates with poor performance status and reduced survival suggesting the involvement of the CD70-CD27 axis." (PMID 40484866, 2025). "Causal effects between CD27 on CD24+ CD27+ cells and CD27 on memory B cells with lung cancer subtypes." (PMID 38962009, 2024). "CD27 on class-switched memory B cells and IgD+ CD24+ B cells were potential risk factors for lung cancer." (PMID 38408977, 2024). "Our analysis identified the expression of CD27 on class-switched memory B cells and IgD+ CD24+ B cells as potential risk factors for lung cancer, using a Bonferroni-adjusted significance threshold of PBonferroni < 0.1." (PMID 38408977, 2024). "A study examining the phenotypes of circulating Tregs and Bregs revealed a decreased frequency of Tregs and an increased frequency of Bregs (including CD24hi CD27+ B cells) in patients with lung cancer." (PMID 38408977, 2024). "In a Lewis lung cancer model, tumor progression was positively correlated with infiltration of CD27-CD11b- NK cells suggesting that the tumor microenvironment locally regulates NK cell maturation process." (PMID 36569860, 2022). "Various TNF family members, including CD40, OX40, 4-1BB, GITR, and CD27, which were investigated as new effective targets, are now under positive exploration for understanding lung cancer." (PMID 36505472, 2022). "In lung cancer specimens, B cell number/proportion increased, with CD27+ subsets enriched." (PMID 41377765, 2025). "In B cells, 138 DEGs were shared by IREB2+ and IREB2+CD27+ cells, and their signature predicted favorable prognosis in lung cancer and LUAD, suggesting IREB2 may suppress malignancy within B cells." (PMID 41377765, 2025). "However, there is also a notable gap in the research concerning the direct impact of CD27 expression on IgD+ CD24+ B cells in the context of lung cancer development." (PMID 38408977, 2024). "It’s suggested that CD24hi CD27+ B cells might promote lung cancer development by suppressing these anti-cancer factors." (PMID 38408977, 2024). "Moreover, high serum soluble CD27 level correlated with poor performance status and reduced survival in patients with advanced lung cancer." (PMID 35019173, 2022). "Indeed, we found elevated JNK phosphorylation in 6Rlo27+ Th17 cells and thus concluded that CD27 suppressed the pro‐inflammatory function of 6Rlo27+ Th17 cells in lung cancer lesions." (PMID 34570961, 2021). "However, more recently lung cancer studies have shown that CD27 expression on human CD4+CD25+ Tregs positively correlates with their suppressive activity in vitro and the expression of FOXP3." (PMID 25951351, 2015).
lung carcinoma (continued). "To further confirm the correlation between the frequency of tumour-infiltrating DN NK cells and the progression of lung carcinoma, we examined the expression of CD11b and CD27 on TINK cells from lung tissue in an intrapleurally implanted murine Lewis lung cancer (LLC) model." (PMID 23565296, 2013). "The phenotyping of pleural effusion CD8+ T-cells from lung cancer patients shows an elevated population of memory (CD45RA−CD45RO+CD27+CD28+) CD8+ T-cells and a low proportion of terminally differentiated (CD45RA+CD45RO−CD27−CD28−) CD8+ T-cells, which is similar to data from TILs." (PMID 23118782, 2012). "Similarly, CD27 on memory B cells also showed increased risks for lung cancer subtypes (for LUAD, ORIVW =1.047; 95% CI: 1.009–1.086; PIVW =0.014; for LUSC, ORIVW =1.053; 95% CI: 1.008–1.099; PIVW =0.020; for SCLC, ORIVW =1.093; 95% CI: 1.002–1.192; PIVW =0.045)." (PMID 38962009, 2024). "Additionally, the increase of CD27 on switched memory B cells and CD27 on IgD+ CD24+ B cells may be linked to lung cancer development." (PMID 38408977, 2024). "The expression of integrin subunit alpha M, CD27, and CCL5 is upregulated in lung cancer tissues with CD163+ cell infiltration." (PMID 37744276, 2023). "Moreover, CD27− B cells can be precursors of CD27+ B cells and vice versa, and the loss or failure to upregulate CD27 in cells correlates with longer, more acidic, and hydrophobic Ab binding sites, and a subset of these cells have been associated with prolonged survival in lung cancer." (PMID 36968223, 2023). "Critically, we observed elevated CD27+ B cells in COPD, suggesting their contribution to cancer progression via inflammatory response modulation and lung microenvironment changes, mirroring their role in lung cancer." (PMID 41377765, 2025). "Notably, 45 overlapping DEGs between COPD B cells and CD27+ subsets suggested roles in COPD–cancer transition, and this signature predicted poor lung cancer/LUAD prognosis." (PMID 41377765, 2025). "Firstly, patients with lung cancer treated with PD-1 inhibitors have a highly specific subset of proliferating CD8+ T cells in the peripheral blood, expressing effector-like phenotypes (HLA-DR+, CD38+, Bcl-2lo), costimulatory molecules (CD28, CD27, ICOS), and high levels of PD-1." (PMID 35484541, 2022).